GPC1 (glypican 1)
Diseases named in the same sentence as GPC1 in open-access papers (continued):
Sharing a sentence is not in itself a finding about the gene and the disease.
cancer (continued). "For investigation of the potential prognostic value of GPC-1 in different cancer types, COX univariate analysis and the Kaplan–Meier plotter were utilized." (PMID 38982153, 2024). "Mass spectrometry analyses have identified the specific enrichment of GPC1 on cancer cell-derived exosomes." (PMID 38720811, 2024). "Recent gene expression studies on clinical patient data reveal that members of the GPC family glypican 1–6 (GPC1–6) undergo specific alterations in cancer." (PMID 38612755, 2024). "The distinct role of GPC1 in promoting the progression of certain types of solid tumors has rendered it an attractive target for cancer therapy." (PMID 38966167, 2024). "Researchers identified and isolated circulating exosomes (crExos) positive for GPC1 from the serum of cancer patients and mice using flow cytometry." (PMID 39596226, 2024). "Although exosomes and exosomal GPC-1 or AM as biomarkers for diagnosing cancers and their induced cachexia still need research in a larger patient group, these discoveries demonstrate the power of exosomes in diagnosing cancers and their complications." (PMID 38689293, 2024). "For instance, Glypican-1 (GPC1) is a membrane-anchored protein in a variety of cancers including PC." (PMID 39113699, 2024). "Together, evidence supporting the potential role of GPC1 as a novel molecular target in cancer holds promise for GPC1 targeted radioimmunotherapy." (PMID 38612755, 2024). "Overall, the expression of GPC-1 in different cancer types have been rationalized differently in different tissues." (PMID 38982153, 2024). "In order to investigate the impact of GPC1 expression on overall cancer survival, continuous Cox Proportional Hazard (CoxPH) model was fitted against GPC1 expression values for each TCGA project." (PMID 36944188, 2023). "Glypican-1(GPC-1) is known to be upregulated in several cancer types in contrast to healthy tissues, rendering it as a biomarker." (PMID 37649964, 2023). "Glypican-1 has been reported to be a cancer exosomal marker, in contrast to our finding that they are mostly associated with nanoparticles." (PMID 37840781, 2023). "Employing a series genetic perturbation experiments including knock-out, knock-down and overexpression assays, we have discovered that downregulation of GPC1 results in attenuation of cell proliferation across different in vitro cancer models." (PMID 36944188, 2023). "KM curves of the survival probability of GPC1 expression strata in the 10 chosen TCGA projects indicate a statistically significant correlation between higher expression level of GPC1 and poor prognosis in all these 10 specific cancer types." (PMID 36944188, 2023). "Based on samples from 26 patients,we found that cancer exosomes such as GPC-1 exosomes are present inmuch higher levels in PDAC patient samples than in healthy ones." (PMID 37470391, 2023). "Glypican-1, encoded by the gene GPC1, is another GPI-AP that we identified as being secreted by a wide variety of cancer cell lines, as well as primary kidney epithelial cells, with a marked enrichment in exomeres and supermeres in comparison to sEVs." (PMID 37840781, 2023). "Further, GPC1 has been shown to undergo recycling and contribute to clearance of oxidative damaged proteins in cancer and neuronal cells." (PMID 36944188, 2023). "This study was designed to increase the knowledge on the potential of GPCs and in particular GPC1 as a biomarker in cancer diagnosis and prognosis." (PMID 36944188, 2023). "For this analysis we considered 10 TCGA cancer types with significant CoxPH results across GPC1 expression levels." (PMID 36944188, 2023). "As our GPC1-targeted CARs showed modest antitumor activity against low GPC1-expressing T3M4 cancer cells, there is a need to improve their potency." (PMID 37031249, 2023).
cancer (continued). "Although both HM2 and D4 CAR T cells exhibited similar killing ability, D4 CAR T cells triggered 2- to 7-fold more secretion of cytokines including IFN-γ, IL-2, and TNF-α than HM2 CAR T cells after exposure to GPC1-positive cancer cells." (PMID 37031249, 2023). "GPC2 belongs to the GPC (GPC1-6) family, which plays a variety of roles in growth factor signaling and cancer cell growth, regulates the growth and development process of the body." (PMID 35795788, 2022). "Studies have suggested that aberrant expression of GPC1 is detected in multiple cancers and that disturbance of GPC1 influences cancer progression." (PMID 36158119, 2022). "While positive staining for WNT7B was observed obviously in the cytoplasm of the majority of malignant tissues, WNT5A, FZD7 and GPC1 signals were presented on both the cytoplasm and membrane of cancer cells." (PMID 35850748, 2022). "Another possibility to take advantage of the characteristics of GPC1 using an mAb is to conjugate it with an anti-cancer drug to obtain an ADC." (PMID 36142190, 2022). "Six species of GPC (GPC1–6) have been identified in mammals, and all of them are shown as cancer therapeutic targets with high expression in cancers." (PMID 35345673, 2022). "Compared to normal pancreatic tissues, the mRNA and protein expression levels of GPC-1 were significantly upregulated in cancer tissues (P < 0.0001 and P < 0.0001, respectively)." (PMID 36313694, 2022). "The ADC was tested on in-vitro and on in-vivo murine models of PDAC, showing high anti-cancer activity in cell lines with high levels of GPC1 compared with those expressing GPC1 at low levels." (PMID 36142190, 2022). "In situ hybridization revealed that GPC1 mRNA expression levels were high in cancer cells and adjacent fibroblasts." (PMID 36142190, 2022). "Further studies revealed the increased expression of GPC1 in prostate cancer, endometrial cancer, lung cancer and other cancers." (PMID 35671267, 2022). "On the basis of this knowledge, researchers began to translate the concept of GPC1 as a cancer marker into tools for diagnosis and treatment." (PMID 34249755, 2021). "With the development of exosomes in caner study, GPC1 has been a resurgence of interest because it is a cancer exosomes specific protein." (PMID 33747908, 2021). "In a study involving 156 patients with PDAC, 199 non‐cancer controls and 240 patients with other cancers, GPC1 and CA19‐9 (carbohydrate antigen 19-9) levels were measured in ELISA." (PMID 34249755, 2021). "This assumption was confirmed when the expression of MIF and GPC-1 proteins in EVs was detected in cancer patients, allowing them to analyze the prognosis of cancer." (PMID 34805181, 2021). "In order to develop a cancer therapy targeting GPC1, we have previously generated anti-GPC1 cytotoxic monoclonal antibodies (mAb) (clone: 1–12)." (PMID 32228854, 2020). "The scientific literature is practically absent of information regarding proteoglycan and pharmacological resistance in cancer, but Saito and colleagues did demonstrate that GBMs with high contents of GPC1 would be positively correlated to MGMT expression." (PMID 32180897, 2020). "Further exploration of the role of GPC1 in RRV-induced cancer development and the possible use of this molecule as a cancer biomarker will provide important insight into the relevance of this molecule to KSHV oncogenesis in humans." (PMID 32017809, 2020). "Evidence showed in the TCM studies suggested that GPC-1 expression in cancer cells is involved in recruitment of specific cells (eg. hMSC and fibroblasts) to the TME to support cancer growth by upregulating migratory and chemokine-tracking factors." (PMID 31391540, 2019). "Earlier studies employed northern blot and immunohistochemistry, and found both GPC-1 mRNA and protein expression levels were elevated in the pancreas with cancer, compared to normal controls and the pancreas with chronic pancreatitis." (PMID 31355137, 2019).
cancer (continued). "Here we provide a brief review about GPC-1 in its expression, signaling and potential as a cancer biomarker." (PMID 31355137, 2019). "Like other glypicans, Glypican-1 (GPC-1) is recently found to be overexpressed in certain cancers, and involved in the tumorigenesis of certain cancers." (PMID 31355137, 2019). "Those pieces of evidence suggest that the presence of GPC-1 is needed to support changes in gene expression in stromal cells, as well as changes in cell morphology in cancer cells in a co-culture model." (PMID 31391540, 2019). "A comparison of exosomes from PC and control cell lines indicated that the exosomes from cancer exhibited enhanced levels of GPC1." (PMID 30671023, 2018). "Since this publication, several different laboratories have validated the concept that glypican-1 is enriched on the EVs derived from cancer cells." (PMID 31162490, 2018). "Recently, our group has identified glypican-1 (GPC1) as a novel cancer antigen for ESCC by quantitative proteomic approach focused on cell surface membrane protein." (PMID 28445969, 2017). "In this study, we analyzed the mRNA and protein expression characteristics of GPC1 in PDAC using the RNA sequencing dataset from the cancer genome atlas (TCGA) and by immunohistochemical staining assays." (PMID 28440066, 2017). "Very recently, the cell surface proteoglycan, glypican-1, was identified as being specifically enriched on cancer exosomes." (PMID 27088079, 2015). "Glypican-1 (GPC1) has emerged as a critical mediator of malignant tumor progression." (PMID 42196164, 2026). "ECM-bound molecules like glypican-1 serve as biomarkers, helping in early cancer detection." (PMID 41281748, 2025). "The GPC-1 mRNA expression profiles in cancer patients were studied using the cBioPortal database." (PMID 38982153, 2024). "In this study, the expression landscape, prognostic analysis, immune infiltration, and clinical staging analysis of GPC-1 in pan-cancer were conducted based on the cBioPortal database, TCGA database, GTEx database, GTEx database, CCLE database, HPA database and TIMER database." (PMID 38982153, 2024). "The findings of this study suggest that GPC-1 influenced the prognosis of patients with cancers and might provide new research directions for cancer treatment." (PMID 38982153, 2024). "Moreover, single-cell data analysis was used to identify the main cell types that express the GPC-1 in cancer microenvironments, and the heatmap demonstrated the expression of GPC-1 of 54 cell types in 176 datasets using the TISCH." (PMID 38982153, 2024). "In addition, K-M survival plots were presented in 33 tumors, and the result showed that the expression of GPC-1 was positively correlated with the prognosis of 3 cancers and negatively correlated with the prognosis of 16 cancers with a P value less than 0.05." (PMID 38982153, 2024). "Further research on immune cell infiltration and GPC-1 expression in other cancer populations might provide additional insights into this question." (PMID 38982153, 2024). "GPC-1 is a cell surface heparan sulfate proteoglycan that interact with a number of ligands to regulate numerous cellular functions and is overexpressed in certain cancers." (PMID 39091874, 2024). "Notably, GPC1 mProtein on the MV surface, particularly tMVs, and GPC1 mRNA in Exos demonstrated the capability to discern between cancer cells and non‐cancer cells or between PDAC patients and healthy donors with significant accuracy." (PMID 38204202, 2024). "Genes that were identified as differentially expressed (Benjamini-Hochberg adjusted p-value <0.05 and absolute log2 Fold Change >0.58) between GPC1-low and GPC1-high patient groups in at least 5 of the studied TCGA cancer types (66 total genes) were then subjected to IPA core analysis." (PMID 36944188, 2023).
cancer (continued). "By optimizing the hinge and transmembrane domains of the nanobody (D4)-based CAR, we have a potent lead GPC1 CAR T candidate that rapidly eliminates low GPC1-expressing xenografts which provides the opportunity for clinical applications in GPC1-positive cancers." (PMID 37031249, 2023). "Furthermore, new evidence suggests that GPC1 expression in bone marrow-derived stromal cells exerts inhibitory effects on cancer cells, making GPC1 a promising target for the development of anti-cancer therapies targeting fibroblast cells." (PMID 37775746, 2023). "Colocalization of GPC-1 and β-tubulin was observed at the tips of leading edges of the cells suggesting GPC-1 may aid in the progression of PDEAC by facilitating migratory properties of cancer cells." (PMID 37649964, 2023). "Indeed, several independent laboratories have reported that in the diagnosis of pancreatic, breast, and colon cancer, GPC1 is enriched in cancer cell–derived exosomes, thus enabling the detection of cancer and possibly response to therapy." (PMID 37953280, 2023). "This couldplay a crucial role in the binding affinity and enables GPC-1 to havehigher specificity to cancer exosomes than healthy ones; therefore,it increases the induced signal in the GFETs biosensors and improvesthe accuracy of detection." (PMID 37470391, 2023). "purified serum exosomes from patients with pancreatic ductal adenocarcinoma (PDAC) and found that all exosome samples of PDAC patients (n = 190) were marked with high expression of GPC-1, suggesting a strong correlation between cancer and serum-derived exosomes." (PMID 35757760, 2022). "Interestingly, while being upregulated in GBM, gpc1 expression was strongly downregulated at 1 dpl, proposing that the feedback loop activated by Gpc1 in cancer cannot be activated during regeneration." (PMID 35223842, 2022). "Glypican-1 (GPC1) is a glycosylated protein recognized as a promising biomarker for cancer." (PMID 36158119, 2022). "However, in many studies with PDAC, the investigation of exosomal GPC-1 was usually combined with other surface markers, which were claimed to possess higher sensitivity and specificity for cancer detection." (PMID 35757760, 2022). "It is likely that the GPC1 signal observed in the fibroblasts could originate from the cancer cells." (PMID 36142190, 2022). "This supports the hypothesis that GPC-1 may be a novel pharmacological target for developing anti-CAF therapeutics to control cancer." (PMID 33927256, 2021). "Here, we show that EV associated glypican 1 expression was similar in plasma from non-cancer controls and OTSCC regardless of nodal status." (PMID 34571828, 2021). "Although GPC-1 can be used as a diagnostic marker and a prognostic indicator in many cancers, the clinical value of GPC-1 in the diagnosis and prognosis of HCC has not been reported." (PMID 33902495, 2021). "The removal of GPC1 from cancer cells which show higher gene expression levels than healthy cells could make these cells insensitive to a number of growth factors." (PMID 33742285, 2021). "GPC1+ circulating exosomes were regarded as a therapeutic target and could facilitate the early detection of cancer." (PMID 33747908, 2021). "Interestingly, there are some studies that have detected GPC1 in cancer cell exome sequencing studies." (PMID 34944807, 2021). "In PDAC, Glypican-1 (GPC1) is highly expressed by cancer cells and CAF." (PMID 34944807, 2021). "The authors also observed that expression of the GPC1 gene in cancer tissue could be partly explained by hypomethylation and gene amplification." (PMID 34249755, 2021). "Additionally, Melo and colleagues identified a cell surface proteoglycan, glypican-1 (GPC1), specifically enriched on cancer cell-derived exosomes." (PMID 33803776, 2021).
cancer (continued). "Recently, we and other groups have reported the overexpression of GPC1 in various human cancers including glioma, mesothelioma, several squamous cell carcinomas (SCC) such as esophageal and cervical cancers, and several adenocarcinomas such as breast and pancreatic cancer." (PMID 32228854, 2020). "Of further significance, GPC1 been found to be enriched in cellular exosomes in several types of cancers, and has been explored for potential use as a biomarker for the early detection of cancer development." (PMID 32017809, 2020). "A variety of genes were identified as being altered in LN tissue samples due to RRV infection, including cancer-associated genes activation-induced cytidine deaminase (AICDA), glypican-1 (GPC1), CX3C chemokine receptor 1 (CX3CR1), and Ras dexamethasone-induced 1 (RasD1)." (PMID 32017809, 2020). "In mice Gpc1 deletion alters brain size and leads to increased risk of cancer, however animals show no skeletal phenotype, as is frequently reported for deleted matrix-associated genes; e.g. Matrilin-3." (PMID 30193893, 2019). "Possible mechanisms of GPC-1 expression in cancer might involve microRNA expression and DNA hypomethylation." (PMID 31355137, 2019). "In addition, few studies had thoroughly examined the relationship between the serum GPC-1 levels and the cancer tissue size, the percentage of GPC-1+ cells, and the GPC-1 concentration of the total cancer tissue homogenate." (PMID 31355137, 2019). "The biomarker potential of circulating GPC-1 was also studied in other cancers." (PMID 31355137, 2019). "Moreover, four primary cancer cell lines were derived from tumors developed in GPC1+/+ (F1015 and F1048) and GPC1−/− (J444 and J1032) mice." (PMID 31681616, 2019). "This prompted us to hypothesize that alteration of GPC-1 expression in cancer cells would affect cancer and stromal responses." (PMID 31391540, 2019). "The authors hypothesized that GPC-1 may be a highly valuable biomarker for incorporation onto a POC test and used as a diagnostic biomarker to facilitate non-invasive cancer detection." (PMID 29865250, 2018). "In other work on PDAC, Glypican-1 was found in exosomes in the context of cancer and could be used to detect early pancreatic cancer." (PMID 30237397, 2018). "Therefore, the detection of GPC-1 will be meaningful in the assessment and the observation of the progression of cancer and neuro-degenerative disorders in general." (PMID 30202003, 2018). "Additionally, multiple antibodies have been identified that can recognise glypican-1 on the surface of cancer exosomes, and validation studies are currently underway." (PMID 31162490, 2018). "In this study, we demonstrated GPC1 as a suitable ESCC cancer antigen for antibody-based therapy." (PMID 28445969, 2017). "Based on the close relationships between GPC3, miR-96-5p, -182-5p, and cancers, we made a hypothesis that miR-96-5p and/or -182-5p might regulate GPC1 expression in the development of PC." (PMID 24736782, 2014). "Moreover, expression of GPC1 promotes cancer growth and metastasis." (PMID 39300946, 2024). "Therefore, GPC1 is a promising target for cancer diagnosis and treatment." (PMID 37827841, 2023). "Hence, our finding that GPC-1 regulates the inflammatory state of HS-5 cells is fascinating as activated fibroblasts have been touted as novel targets for resolving inflammation in cancer and other inflammatory diseases." (PMID 33927256, 2021). "Glypican-1-positive exosomes may therefore serve as a tool for early detection of cancer." (PMID 33330449, 2020). "Thus, Miltuximab® conjugates may have utility as theranostic agents in patients with PCa and potentially for other cancers which express GPC-1." (PMID 32382920, 2020). "Moreover, anti-GPC-1 mAb was rapidly internalised into the cancer cells after GPC-1 bound to them." (PMID 32152502, 2020). "Thus, GPC-1 expression is necessary to enable GPC-1-ADC to inhibit cancer cell growth." (PMID 32152502, 2020).